BACH2 (BACH transcriptional regulator 2)
Diseases named in the same sentence as BACH2 in open-access papers (continued):
Sharing a sentence is not in itself a finding about the gene and the disease.
Sepsis (1 paper, 2023). Sepsis is defined as life-threatening organ dysfunction caused by a dysregulated host response to infection. "In this study, BACH2 was also identified as a hub gene involved in sepsis and associated with immune infiltration." (PMID 37091800, 2023). "In the present study, we identified 47 DE-NRGs between sepsis and healthy control in the dataset GSE65682 and screened out 4 hub genes (BACH2, GATA3, LEF1, and BCL2) via various machine learning algorithms." (PMID 37091800, 2023). "In the study, we found that 4 necroptosis-related hub genes (BACH2, GATA3, LEF1, and BCL2) were closely related to sepsis, providing a potential new target for the diagnosis and therapy of sepsis." (PMID 37091800, 2023). "In conclusion, using machine learning analysis we identified 4 necroptosis-related hub genes (BACH2, GATA3, LEF1, and BCL2), which could be used as the potential di-agnostic and prognostic biological marker in sepsis." (PMID 37091800, 2023).
T-cell acute lymphoblastic leukemia (1 paper, 2023). Acute lymphoblastic leukemia of T-cell origin. "KDM2B is known to enhance terminally Th17 cell formation and is involved in maintenance of T-cell acute lymphoblastic leukemia, which all could support the role of a phenotypic dysfunctional exhausted T cell type in the clusters without BACH2." (PMID 36879901, 2023).
thyroid (1 paper, 2025). "Emerging evidence suggests a potential molecular link between AT and thyroid malignancies, characterized by the co-expression of multiple genes such as TSHR, BTB domain and CNC homolog 2 (BACH2), and forkhead box E1 (FOXE1), along with shared somatic mutations." (PMID 41153734, 2025).
thyroid cancer (1 paper, 2021). "Among them, there were 7 mutation sites of importance for HT-related genes [CTLA4 (1 site), BACH2 (3 sites), and RNASET2 (3 sites)] where at least two patients with thyroid cancer experienced mutations." (PMID 34993154, 2021). "Our research group used bioinformatics to analyze the Oncomine database and found that HT-related genes (TSHR, BACH2, RNASET2, CTLA4, PTPN22, IL2RA) were expressed in different types of thyroid cancer." (PMID 34993154, 2021). "Among them, TSHR and RNASET2 were highly expressed in malignant tumors, especially TSHR in thyroid cancer, while BACH2, CTLA4, PTPN22, IL2RA, and other immune-related genes are expressed significantly lower in thyroid cancer." (PMID 34993154, 2021).
tuberculosis (1 paper, 2024). A chronic, recurrent infection caused by the bacterium Mycobacterium tuberculosis. "When IL-7 was added to the traditional tuberculosis vaccine, treatment with the recombinant adeno-associated virus (rAAV)-IL-7 mixed subunit vaccine resulted in significantly increased Bach2 expression at the beginning of CD8 + T-cell development." (PMID 38459508, 2024).
venous thromboembolism (1 paper, 2023). Occlusion of the lumen of a vein by a thrombus that has migrated from a distal site via the blood stream. "We chose to quantify ANXA3, TNFAIP6, TXK, BACH2, and SERPINB2 mRNA expression in t-PAPS based on the results of a meta-analysis using a bioinformatics panel to explore the differences and similarities between venous thromboembolism (VTE) and cardiovascular disease." (PMID 37035297, 2023).
Venous thrombosis (1 paper, 2023). Formation of a blood clot (thrombus) inside a vein, causing the obstruction of blood flow. "Recently, dysregulation of the ANXA3, TNFAIP6, TXK, BACH2, and SERPINB2 genes has been associated with both arterial and venous thrombosis in the general population." (PMID 37035297, 2023). "In the meta-analysis that inspired this study, the association between BACH2 and SERPINB2 with arterial and venous thrombosis was weaker than that of the other genes." (PMID 37035297, 2023).
visceral leishmaniasis (1 paper, 2018). A severe form of leishmaniasis characterized by irregular bouts of fever, substantial weight loss, swelling of the spleen and liver, and anemia (which may be serious). "Therefore, we also investigated the role of BACH2 in visceral leishmaniasis (VL) caused by infection with the human protozoan parasite Leishmania donovani to establish how broadly applicable our findings were." (PMID 30459773, 2018).
tumor (61 papers, 2009 to 2026). "The tumor suppressor Menin, prone to mutations in both hereditary and sporadic endocrine tumors, along with its direct target Bach2, plays a crucial role in preventing autoimmunity by regulating CD4 + T cell senescence and maintaining cytokine homeostasis." (PMID 40128849, 2025). "Studies have highlighted its crucial involvement in tumor immunosuppression, where BACH2-deficient mice implanted with tumors exhibit markedly reduced tumor growth compared with their wild-type counterparts." (PMID 38891024, 2024). "Bach2-deficient NK cells also displayed increased cytotoxic gene expression and chromatin accessibility and were more potent in controlling tumor metastases." (PMID 36190189, 2022). "In summary, NK cells in Bach2-deficient mice are more efficient in controlling tumor progression and metastasis in the lung." (PMID 36190189, 2022). "Further analysis revealed that suppression of IFNγ is caused by BACH2-mediated Treg-dependent tumor immunosuppression." (PMID 31824865, 2019). "Quantitative PCR and western blot analysis confirmed loss of Bach2 in c-Rel mutant Eμ-Myc tumours at both 4 weeks and the terminal stages of disease." (PMID 26522720, 2016). "In addition to affecting adaptive immunity, deficiency of BACH2 expression promotes natural killer (NK) cell maturation, regulates its function, and suppresses tumor metastasis in mice." (PMID 37228820, 2023). "Consequently, Bach2-deficient mice exhibit markedly impaired tumour growth due to increased effector T cell activation and a reduction in TRegs." (PMID 33549134, 2021). "Similarly, during the course of the B-cell development, BACH2 has also been reported to play significant cell cycle and apoptotic regulatory roles, suggesting a possible tumour suppressor function for BACH2 in good risk subgroups of CLL." (PMID 35008187, 2021). "Thus, the Foxp3 + Treg population exhibited a trend toward a significant reduction in tumour density in Bach2-deficient animals reveals therapeutic targets for reversing cancer immunosuppression and is unquestionably a critical part of the molecular pathway involved in tumour immunosuppression." (PMID 38459508, 2024). "BTB and CNC homology 2 (BACH2) is a lymphoid-specific transcription repressor recognized as a tumor suppressor in B-cell malignancies, but little is known about its function and regulatory network in T-ALL." (PMID 38233409, 2024). "Further in vitro and in vivo experiments confirmed a tumor-suppressor-like role of BACH2 in T-ALL progression and organ infiltration." (PMID 38233409, 2024). "We also revealed for the first time the BACH2-CD28 and BACH2-CD40LG axes in the progression and dissemination of T-ALL, adding a new layer to the landscape of BACH2-mediated tumor immunoregulation in T-cell malignancies." (PMID 38233409, 2024). "BACH2’s significance extends beyond murine tumor models, as it also plays a pivotal role in human cancers." (PMID 38891024, 2024). "While no specific integration into cancer gene regions was observed in the analysis of CAR gene insertion sites, integration into the BACH2 gene region, considered a tumor suppressor gene, was observed in both cases." (PMID 38545443, 2024). "This underscores BACH2’s impact on tumor progression and the modulation of immune responses within the tumor microenvironment." (PMID 38891024, 2024). "There is evidence that Bach2 suppresses the induction of appropriate innate and adaptive immunity and promotes tumour growth in a tumour cell-extrinsic manner." (PMID 38459508, 2024). "BACH2 exerts multifaceted effects in tumor immunosuppression and cancer pathogenesis, influencing diverse aspects of immune cell function and tumor biology." (PMID 38891024, 2024). "Through a mechanism known as Treg-mediated inhibition of intratumoral CD8 + T cells and interferon γ (IFN-γ), Bach2 supports tumour immunosuppression." (PMID 38459508, 2024).
tumor (continued). "More importantly, BACH2-mediated CD28 and CD40LG signals contributed to cell migration and dissemination of T-ALL cells to the bone marrow, thus adding a new layer to the BACH2-mediated tumor immunoregulation in T-cell malignancies." (PMID 38233409, 2024). "BACH2 maintains immune homeostasis and durable tumor immunosuppression and induces cancer progression by regulating Treg and NK cells in gastrointestinal tumors." (PMID 37228820, 2023). "This instability in the host genome leads to the loss of some host genes, like the BTB domain and CNC homolog 2 (BACH2), that are associated with tumor suppressor genes and are probably involved in lymphomagenesis." (PMID 36880311, 2023). "BACH2 affects tumor progression and immune-related benign diseases by regulating the differentiation and function of immune cells." (PMID 37228820, 2023). "BACH2 proteins promote immune homeostasis and long-term tumor immunosuppression by driving the quiescence and durable maintenance of resting Treg cells." (PMID 37228820, 2023). "In combination, these results appear to reflect the experimental observation of the tumor suppressor role of BACH2 and the dual regulation role of BCL6." (PMID 37374114, 2023). "Such a shift of AHR enrichment peaks was exampled by the AHR peaks on the BACH2 gene encoding a BTB domain basic leucine zipper transcription factor important for cell apoptosis and tumor immunosuppression." (PMID 37151890, 2023). "To determine if Bach2 deficiency in NK cells resulted in better direct killing of B16F10 cells, we performed in vitro tumor killing assays with B16F10 cells." (PMID 36190189, 2022). "In MCL, HIF-1α participates in the downregulation of BACH2, which not only accelerates tumor formation but also promotes tumor spread to the spleen and bone marrow." (PMID 34404434, 2021). "The clinical outcome and the proteomic data highlight the tumour suppressor role and the functional significance of BACH2 and BCL6 in CLL biology." (PMID 35008187, 2021). "Further study identified that the subcellular localization of BTB and CNC homology 2 (BACH2), a lymphoid-specific transcription repressor recognized as a tumor suppressor in MCL, determines oxidative stress responses to BTZ in MCL." (PMID 34039348, 2021). "The nuclear BACH1 expression is associated with adverse clinical features in DLBCL, whereas BACH2 has been well-recognized as a tumor suppressor in many hematological malignancies." (PMID 34039348, 2021). "Previous studies have shown that BACH2 facilitates tumor growth by promoting tumor immunosuppression." (PMID 33875646, 2021). "For comparison with BCL6 and in vitro data, gene expression analysis of BM-derived tumor cell populations was subsequently performed for BACH2." (PMID 32131762, 2020). "For MSI-H patients, our analysis indicated that the BACH2 gene was significantly up-regulated and correlated with high grade tumor (Grade 3 and T3+T4) and poor survival outcome in patients." (PMID 33316777, 2020). "BACH2 is a B‐cell‐specific transcriptional inhibitor that acts as a tumour suppressor in B‐cell malignancy." (PMID 32892482, 2020). "Genetic deletion of Bach2 in mice results in increased clearance of subcutaneously syngeneic B16 melanoma tumours." (PMID 33144667, 2020). "Recent research found that BACH2 promotes tumor immunosuppression via IFNγ and Treg-mediated intratumoral CD8+ T cell inhibition." (PMID 31824865, 2019). "Regulating B cell development at the pre-B cell receptor checkpoint BACH2 functions as a tumor suppressor in B-ALL." (PMID 30841886, 2019). "Our results identify the role of SENP3-triggered BACH2 deSUMOylation in the cross-talk between ROS and Treg cell-mediated tumor immunosuppression." (PMID 30089837, 2018). "Canonical NF-κB can also inhibit tumor growth by inducing the expression of tumor suppressors such as Bach2 induced in B-cells by c-Rel or RelA suggesting a tumor suppressive function of c-Rel in B-cell lymphoma." (PMID 29601548, 2018).
tumor (continued). "One of the important findings of this study was the identification of BACH2 as a potential key player in the aggressiveness of WM tumor cells." (PMID 28924457, 2017). "BACH2 is a tumor suppressor and it is reported to be frequently inactivated in primary pre-B ALL patients via promoter hyper-methylation, missense mutations and deletions, as well as via loss of its upstream regulator paired box 5 (PAX5)." (PMID 28030830, 2017). "Here, we found that Ikaros, a tumor suppressor encoded by IKZF1, directly binds to both the BCL6 and BACH2 promoters where it suppresses BCL6 and promotes BACH2 expression in B-cell ALL (B-ALL) cells." (PMID 28030830, 2017). "Although a direct link between HIV integration and oncogenic transformation has not been established, there is, in the literature, a report of a tumor which has an HIV integration in BACH2." (PMID 27682062, 2016). "In normal spleen the level of the Bach2 cDNA derived from the normal promoter was comparable with the cDNA level in tumor 1206 whereas the amount of the alternative promoter derived Bach2 cDNA was present in a low amount." (PMID 19159451, 2009). "We notice a lower level of Bach2 mRNA expression in all tumor samples compared to the normal spleen control." (PMID 19159451, 2009). "It should be noted that the transcriptional orientation of the provirus in tumor 1206 was opposite to that of Bach2, thus minimizing the possibility that the virus directly contributed such an alternative promoter." (PMID 19159451, 2009). "Bach2 transcripts including this exon 4 L was detected in tumor 1206 material as well as in other tumor samples, and also in normal mouse spleen (data not shown)." (PMID 19159451, 2009). "The amount of Bach2 transcripts derived from the alternative promoter was similar in all types of tumor tissues examined from mouse 1206." (PMID 19159451, 2009). "To examine if the alternative Bach2 promoter was active only in tumor 1206 material, we screened RNA from several tumors for the presence of such an alternative Bach2 transcript." (PMID 19159451, 2009). "In consistence with its role as a putative tumor suppressor, Bach2 was found to induce apoptosis in response to oxidative stress." (PMID 19159451, 2009). "The alternative promoter was active in both normal and tumor tissue and the tissue specificity of the two Bach2 promoters was similar." (PMID 19159451, 2009). "Albeit semi-quantitative, the assay also pointed at an up-regulation of alternative Bach2 promoter in tumor 1206 as compared to the other examined tissue samples." (PMID 19159451, 2009). "Using a primer pair covering exons 7 to 8, we noticed the same tendency, except for tumor 1206, which displayed a marked increase in Bach2 mRNA expression, compared to that of the other tumor samples and normal spleen." (PMID 19159451, 2009). "Besides, considering the pathological role of BACH2 in tumor immunosuppression, an attempt to target this repressor was deemed necessary." (PMID 42077849, 2026). "In conclusion, we revealed a tumor-suppressor-like role of BACH2 in T-ALL cells and xenografts." (PMID 38233409, 2024). "Bach2 is also a crucial factor for promoting immune suppression within tumours." (PMID 38459508, 2024). "In this way, BACH2 promotes tumor growth in colorectal adenocarcinoma." (PMID 37228820, 2023). "Upstream regulator analysis comparing RNA sequencing data from PKM2KO and PKM2WT T cells isolated back from mouse tumors after adoptive co-transfers and from AG1 and DMSO treated T cells isolated after in vitro co-culture with tumor cells demonstrated conserved Foxo1 and Bach2 signatures." (PMID 37790365, 2023). "Moreover, BACH2 (induced by c-Rel/NF-κB) functions as a tumour suppressor in the early stages of B-cell lymphoma development." (PMID 35008187, 2021). "However, the clear trend observed in this overall survival study suggests a promising tumour suppressor function for BACH2 and BCL6." (PMID 35008187, 2021).
tumor (continued). "BACH2 is a lymphoid-specific transcription repressor recognized as a tumor suppressor in MCL." (PMID 34039348, 2021). "In addition, BACH2 promotes tumor growth through tumor immune suppression of Treg-mediated CD8+ T cells." (PMID 33316777, 2020). "MS4A1 (CD20, tumor infiltrating B-cell marker), and BACH2 (a well-known transcriptional regulator of B and TFH cells), two genes previously implicated in contributing to immune landscape differences between RSCC and LSCC, are more predominantly suppressed within distal tumors." (PMID 32293332, 2020). "BACH2 is upregulated in tumours of patients with PD‐1 response‐responsive renal cell carcinoma." (PMID 32892482, 2020). "In similar results from our previous study, we demonstrated that BACH2 could play a role as a tumor suppressor gene by increasing the apoptosis of CD4+ T-cells in vitro." (PMID 30654767, 2019). "Epigenetic modulation of the BACH2/BCL6 axis may therefore be an additional mechanism to regulate tumor cell apoptosis and proliferation." (PMID 30841886, 2019). "In addition, the percentage, IFN-γ production, BACH2 SUMOylation or suppressive function of tumor-infiltrating Treg cells from Foxp3-CreSenp3f/f mice treated with or without NAC displayed no apparent difference." (PMID 30089837, 2018). "These DEGS included BACH2, a gene involved in T cell regulation and tumor suppression." (PMID 30586396, 2018). "Oncogenic processes may corrupt the balance of the apoptotic-signalling pathway under BACH2 control leading to cell proliferation and tumour progression." (PMID 29129929, 2017). "Within this expression profile, BACH2 was identified as a candidate gene that may help to understand better the behavior of tumor cells in indolent WM." (PMID 28924457, 2017). "Bach2 protein levels were also significantly reduced in the Eμ-Myc/c-rel−/− tumours." (PMID 26522720, 2016). "Significantly lower expression of BACH2 -mRNA as well as -protein in these bortezomib resistant MCL cell lines compared to bortezomib sensitive MCL cells as well as patient cells suggested that BACH2 might function as a tumor suppressor in MCL cells." (PMID 23936317, 2013). "Some of these aberrant SHMs may occur at proto-oncogenes, such as BCL6 and/or tumor suppressors i.e. BACH2, giving cells growth advantages and eventually leading to malignant transformation." (PMID 22808135, 2012). "Also for primer combinations spanning Bach2 exons 4 to 5 and exons 3 to 4 an up-regulation of Bach2 expression in tumor 1206 was evident as compared to the other tumor samples." (PMID 19159451, 2009). "Several lines of evidence indicate that Bach2 is a B-cell specific tumor suppressor." (PMID 19159451, 2009). "Moreover, we found that in tumor 1206 material the expression level of the Bach2 transcript derived from the alternative promoter was similar to the expression level the Bach2 transcript driven from the normal promoter." (PMID 19159451, 2009). "Several lines of evidence show that Bach2 is a B-cell specific tumor suppressor." (PMID 19159451, 2009). "Indeed, we were able to identify such a novel Bach2 promoter and in accordance with the expression data we observed increased expression within tumor material from mouse 1206." (PMID 19159451, 2009). "In cDNA synthesised from tumor 1206 mRNA the amount of the two types of Bach2 cDNA was comparable." (PMID 19159451, 2009). "Thus, in tumor 1206, a preferential up-regulation of Bach2 transcripts including exon sequences spanning exon 3 to exon 8 was observed." (PMID 19159451, 2009). "However, another study found that low‐dose ALA‐PDT could repair DNA damage in UVA‐induced skin photoaging, possibly by upregulating the Bach2 protein through low levels of ROS." (PMID 39044341, 2024). "Additionally, the transplanted tumour in the sh‐BACH2+sh‐FUS+TSLNC8‐OE group was the smallest." (PMID 32892482, 2020).